PIEZO1 (piezo type mechanosensitive ion channel component 1 (Er blood group))
Diseases named in the same sentence as PIEZO1 in open-access papers (continued):
Sharing a sentence is not in itself a finding about the gene and the disease.
channelopathy (continued). "In support, PIEZO2 channelopathy-derived impaired PIEZO2-PIEZO1 crosstalk downregulates PIEZO1 on certain cells, like dendritic cells, and upregulates PIEZO1 on other cells, like satellite/astrocyte cells within the affected compartments or organs with blood barriers." (PMID 39682086, 2024). "Most likely, Piezo1 channelopathy is also a transcription activator, and it is also important to note that Piezo1 channelopathy could also induce Piezo2 channelopathy under prolonged stress-induced mechanotransduction." (PMID 38534336, 2024). "The current authors suggest that this disruption in regeneration of nerve fibers could have been the result of impaired crosstalk between corneal somatosensory-terminal Piezo2 and peripheral-cell Piezo1 due to chronic Piezo2 channelopathy." (PMID 37108693, 2023). "However, chronic Piezo2 channelopathy not only keeps transcription activated and wound healing unfinished, but is also postulated to disrupt the crosstalk with Piezo1 of peripheral cells." (PMID 37445856, 2023). "The authors of this manuscript propose that the observed corneal sensory morphology could have been the result of impaired crosstalk between corneal somatosensory-terminal Piezo2 and peripheral-cell Piezo1 due to chronic Piezo2 channelopathy." (PMID 37108693, 2023). "Not to mention that Piezo2 channelopathy is also suggested to be associated with impaired crosstalking between Piezo1 and Piezo2, beyond being a principal transcription activator." (PMID 37445856, 2023). "The theorized peripheral intrafusal Piezo2 channelopathy-induced transient disruption of Piezo1–Piezo2 crosstalk and NMDA activation in DOMS could be the reason why orthostasis may be impaired." (PMID 37999426, 2023). "Piezo2 channelopathy could result in the imbalanced control of Piezo1 on keratinocytes in a clustered manner, leading to dysregulated keratinocyte proliferation and differentiation." (PMID 36233237, 2022). "According to this Piezo2 channelopathy theory, Piezo2 ion channels should be considered as homeostatic gatekeepers of peripheral sensory neuron terminals in a compartmental micro-milieu, whereas Piezo1 ion channels are the homeostatic gatekeepers of the surrounding peripheral cells." (PMID 37895134, 2023). "Furthermore, Piezo1 upregulation in activated keratocytes due to chronic Piezo2 channelopathy and impaired Piezo crosstalk could also lead to an imbalance in the Th17/Treg ratio, contributing to DED." (PMID 37108693, 2023). "Consequently, the impaired Piezo2–Piezo1 crosstalk resulting from acquired Piezo2 channelopathy may lead to the abrogation of proper Piezo1 modulation, which could, in turn, result in insulin resistance, given that Piezo1 is involved in glucose-induced insulin secretion." (PMID 40137805, 2025). "As a result of chronic Piezo2 channelopathy, upregulation of Piezo2 in affected dorsal root ganglions (DRG) and upregulation of Piezo1 on peripheral cells, such as keratinocytes, is suspected." (PMID 36983813, 2023). "Here, we report several near-atomic resolution cryo-EM structures of fast-inactivating wild-type human PIEZO1 (hPIEZO1) and its slow-inactivating channelopathy mutants with or without its auxiliary subunit MDFIC." (PMID 40668110, 2025). "Moreover, PIEZO2 channelopathy impairs PIEZO2-PIEZO1 crosstalk within a compartmental micromilieu, and astrocytes contain PIEZO1 even in the hippocampus." (PMID 39682086, 2024). "Moreover, the current authors postulate that Piezo1 in activated corneal keratocytes could be upregulated in a feed-forward manner in DED, as was suggested in psoriasis, due to chronic Piezo2 channelopathy and impaired Piezo crosstalk." (PMID 37108693, 2023). "Therefore, DED could be initiated by a chronic Piezo1 channelopathy, but could also evolve into an NCP, which is considered primarily a Piezo2 channelopathy, constituting the nociceptive continuum paradox." (PMID 35507012, 2022).
lymphedema (21 papers, 2015 to 2025). Excess fluid collection in tissues, causing swelling. "In terms of angiogenesis, the gene PIEZO1, which encodes a vascular mechanosensory channel, is implicated in vascular development and maturation, associated with VVs and lymphedema." (PMID 41391741, 2025). "In fact, the only gene identified in this study known to be associated with a Mendelian disease that results in VVs is PIEZO1, which also predisposes to both VVs and lymphoedema." (PMID 35654884, 2022). "Loss-of-function mutations in PIEZO1 also account for hydrops fetalis, chylothorax, and chronic pleural effusions with persistent lymphedema of legs, torso, and face." (PMID 30930797, 2019). "Another area to consider is lymphoedema because loss‐of‐function mutations in PIEZO1 are associated with generalised lymphatic dysplasia, and so PIEZO1 agonists might be beneficial if partly functional channels are still available." (PMID 36457143, 2023). "However, the analysis of the fetus’s muscle cells revealed greatly attenuated PIEZO1 expression, which strongly implicated impaired PIEZO1 function–associated hereditary lymphedema." (PMID 35646098, 2022). "Mutations in the mechanically activated ion channel PIEZO1 are associated with human lymphedema." (PMID 27313318, 2016). "In PIEZO1 variant-associated GLD, venous varicosities are reported, and VVs have been associated with another type of lymphedema, called lymphedema distichiasis." (PMID 40628291, 2025). "Associations are suggested with body mass index, obesity and dyslipidaemia, which are consistent with observations in Piezo1 genetically modified mice and relevant to lymphedema and VVs." (PMID 40628291, 2025). "Genetic mutations in PIK3CA, ARAP3, PIEZO1, and PTEN also play important roles in the PI3K/AKT signaling pathway in the development of lymphedema." (PMID 40766782, 2025). "In humans, similar to PIEZO1, mutations in FLT4, ANGPT2, and TIE1 have been associated with lymphedema, underscoring the conservation of function across species." (PMID 38747287, 2024). "Here we report homozygous and compound heterozygous mutations in PIEZO1, resulting in an autosomal recessive form of GLD with a high incidence of non-immune hydrops fetalis and childhood onset of facial and four limb lymphoedema." (PMID 26333996, 2015). "The observation of lymphoedema provides evidence of a role for PIEZO1 in the development of lymphatic structures." (PMID 26333996, 2015). "When the PIEZO1 disruption is strong, there may be early onset lymphedema and then late onset VVs that are both direct independent consequences of PIEZO1 disruption." (PMID 40628291, 2025). "When the PIEZO1 disruption is partial, there may be only late-onset disease that is characterized by VVs and lymphedema; in this case, the lymphedema could be both a direct consequence of the PIEZO1 disruption and the increased venous pressure." (PMID 40628291, 2025). "In mouse, loss of Piezo1 reduces LvEC cell‐cell adhesion leading to defects in cellular condensation and a failure to form a ring‐like constriction, while PIEZO1 mutations are associated with lymphedema in humans." (PMID 34716915, 2021). "Variable expression has been observed in other primary lymphedemas, e.g., PIEZO1-related LRHF/GLD." (PMID 27400125, 2016). "Through whole-exome sequencing, we identify biallelic mutations in PIEZO1 (a splicing variant leading to early truncation and a non-synonymous missense variant) in a pair of siblings affected with persistent lymphoedema caused by congenital lymphatic dysplasia." (PMID 26387913, 2015). "Piezo1 was of interest for several reasons: (a) it is activated by mechanical forces including OSS, and (b) mutations in this gene have been identified in patients with lymphedema, and mice lacking PIEZO1 develop lymphatic defects, including failure of valve formation." (PMID 38747287, 2024).
lymphedema (continued). "KIF11 heterozygous nonsense mutations cause microcephaly with or without chorioretinopathy, lymphedema, or mental retardation (OMIM: 152950), while PIEZO1 homozygous or compound heterozygous loss-of-function mutations cause lymphatic malformations 6 (OMIM: 616843)." (PMID 35806420, 2022).
anemia (20 papers, 2019 to 2025). A reduction in the number of red blood cells, the amount of hemoglobin, and/or the volume of packed red blood cells. "Beyond its physiological functions, Piezo1 dysfunction is associated with Hereditary Xerocytosis, a rare haemolytic but mostly compensated anaemia caused by gain-of-function mutations in Piezo1 and characterised by dehydrated RBCs." (PMID 40867555, 2025). "In human populations, gain-of-function (GOF) mutations in PIEZO1 represent the most common genetic cause of hereditary xerocytosis (HX), a rare disorder frequently complicated by iron overload and compensatory anemia." (PMID 41237237, 2025). "The second variant calling step (117 anaemia-related genes) identified an additional likely pathogenic variant in PIEZO1 in patient 6-1." (PMID 38069343, 2023). "Generalized lymphatic dysplasia, which also manifests itself in varying degrees of anemia in addition to defects in lymphatic development, results from loss-of-function Piezo1 mutations characterized by reduced sensitivity to the applied mechanical force." (PMID 35340591, 2022). "According to recent research, mutations in the PIEZO1 gene of humans contribute to anemia (dehydrated stomatocytosis) and generalized lymphatic dysplasia." (PMID 30745454, 2019). "Human PIEZO1 gene mutations resulted in anemia and generalized lymphatic dysplasia, and PIEZO2 gene mutations were proved to cause distal arthrogryposis and other diseases." (PMID 30745454, 2019). "Similarly, a retrospective study of 126 individuals diagnosed with Piezo1-HX pointed to high variability in the clinical expression of Piezo1 mutation with clinical manifestations that include anemia, splenomegaly, and post-splenectomy thrombosis." (PMID 41440018, 2025). "In addition, mutations in the Piezo1 gene are closely related to the occurrence and development of type B marine anemia by affecting red blood cell function." (PMID 38690080, 2024). "Piezo1 was found to be strongly linked to a variety of anemia." (PMID 38690080, 2024). "Whether this anemia was precipitated by PIEZO1 variant, which would be a novel presentation, remains unknown as neither fetal nor parental erythrocytes were examined." (PMID 36959127, 2023). "Hereditary Xerocytosis, a familial anemia, is caused by a gain-of-function mutation in Piezo1 characterized by slowed inactivation resulting from three missense mutations and one recurrent duplication in the Piezo1 gene, with all mutations located at the C-terminal half of Piezo1." (PMID 35340591, 2022). "Furthermore, gain-of-function (GOF) mutations in human Piezo1 cause hereditary xerocytosis (also known as dehydrated stomatocytosis), a familial anemia, whereas loss-of-function (LOF) mutations cause generalized lymphatic dysplasia characterized by varying degrees of anemia." (PMID 31494839, 2019). "Gain-of-function PIEZO1 mutations are associated with dehydrated hereditary stomatocytosis (DHS), a type of anaemia, due to abnormal red blood cell function." (PMID 35406763, 2022). "Gain-of-function mutations in Piezo1 have been associated with human DHS, characterized by severe dehydration, RBC atrophy, and anemia." (PMID 33935792, 2021). "Morpholino-knockdown of Piezo1 expression in Danio rerio was reported to result in severe anemia." (PMID 30930797, 2019). "Of note, a comprehensible hematological characterization of the anemia carried by patients with PIEZO1 loss-of-function mutations has not yet been performed." (PMID 30930797, 2019). "In addition to myocardial iron deposition, PIEZO1 GOF variants may impair red blood cell turnover and contribute to anemia, which is often compensated and subclinical, yet may still contribute to the development of cardiomyopathy over time." (PMID 41237237, 2025). "Interestingly, Piezo1 is related not only to anemia but also to the prevention of malaria." (PMID 38690080, 2024).
anemia (continued). "Nonetheless, mice with systemic overexpression of Piezo1 did not develop anemia, morphological changes in RBCs, or splenomegaly, which may reflect differences in the effects of Piezo1 activation as a congenital condition versus during adulthood." (PMID 40533105, 2025). "Considering proband A (V222L mutation), the non-regenerative anemia may be due to either a non-identified intercurrent cause, or a role of KCNN4 during erythropoiesis, as described for PIEZO1-related DHSt." (PMID 36003639, 2022).
hereditary xerocytosis (20 papers, 2015 to 2025). "Knockouts of PIEZO1 are embryonic lethal, and PIEZO1 mutations are associated with several diseases, including dehydrated hereditary stomatocytosis, and lymphatic dysplasia." (PMID 39844465, 2025). "Gain-of-function mutations in PIEZO1 have been linked to Dehydrated Hereditary Stomatocytosis (DHSt), a rare red blood cell (RBC) disease also known as hereditary xerocytosis." (PMID 34737711, 2021). "The first disease related to Piezo was demonstrated in 2012, and it was reported that mutations in Piezo1 are associated with hereditary xerocytosis." (PMID 33722169, 2021). "Gain-of-function mutations within PIEZO1 cause prolonged opening of the PIEZO1 channel upon activation, and are associated with an autosomal dominant disease called Hereditary Xerocytosis (HX)." (PMID 33478008, 2021). "Different missense gain-of-function mutations in PIEZO1 gene have been identified that cause Hereditary Xerocytosis (HX), a rare autosomal dominant haemolytic anemia." (PMID 32848880, 2020). "Individuals diagnosed with Dehydrated Hereditary Stomatocytosis (DHSt) were found to have a missense mutation in a conserved arginine residue (R2488Q) of PIEZO1." (PMID 32490809, 2020). "For example, defects in the calcium activated Gardos channel (KCNN4) and the mechanosensitive cation channel (PIEZO1) are known to cause hereditary xerocytosis, an autosomal dominant hemolytic anemia." (PMID 33370780, 2020). "The focus of this study is on Piezo1, a newly discovered, large, mammalian, mechanosensitive ion channel, which has been linked to diseases such as dehydrated hereditary stomatocytosis (Xerocytosis) and lymphatic dysplasia." (PMID 30885080, 2019). "Another example is Piezo1—this mechano-sensitive channel was only recently discovered and associated with the anemic disease hereditary xerocytosis (HX) due to mutations of Piezo1 found in HX patients." (PMID 26322315, 2015). "Inspired by one of the reviewers, it is suggested that the osmoscan may help differentiate between NAS patients and patients with PIEZO1 mutations [hereditary xerocytosis (HX)]." (PMID 39091345, 2024). "The presence of the PIEZO1 channel in human RBC membranes was first established from the link between gain-of-function mutations of PIEZO1 and a RBC pathology, termed Dehydrated Hereditary Stomatocytosis (DHS) or Xerocytosis." (PMID 37492641, 2023). "Mutant PIEZO1 channels in hereditary xerocytosis (HX) were found to exhibit a number of kinetic abnormalities the most prominent of which was a marginally reduced inactivation kinetics following brief stretch-activation pulses." (PMID 33690597, 2021). "Along the same line of argumentation, when mutations or variants of Piezo1 are measured, i.e., when RBCs from patients with Hereditary Xerocytosis are investigated, we know that Piezo1 presents an altered activity and hence, the EC50 for Yoda1 and Yoda2 will be different." (PMID 40867555, 2025). "In 2012–2013, PIEZO1 was identified by exome sequencing as a causative gene of both isolated and syndromic forms of dehydrated hereditary stomatocytosis (DHS, also known as hereditary xerocytosis)." (PMID 34779027, 2022). "Mutations in human PIEZO1 and PIEZO2 can lead to a variety of hereditary diseases, including Piezo1-based dehydrated hereditary stomatocytosis (DHS) and generalized lymphatic dysplasia, and Piezo2-based distal arthrogryposis syndrome, Gordon syndrome and Marden-Walker syndrome." (PMID 33935792, 2021). "Hereditary Xerocytosis, a rare hemolytic anemia, is due to gain of function mutations in PIEZO1, a non-selective cation channel activated by mechanical stress." (PMID 34737711, 2021). "Mutations in both human PIEZO1 and human PIEZO2 have been identified among patients suffering from channelopathy diseases, such as dehydrated hereditary stomatocytosis (DHSt), generalized lymphatic dysplasia (GLD), and distal arthrogryposis type 5 (DA5), in which osmoregulation is disturbed." (PMID 32490809, 2020).